HOTAIR (HOX transcript antisense RNA)
Diseases named in the same sentence as HOTAIR in open-access papers (continued):
Sharing a sentence is not in itself a finding about the gene and the disease.
tumor (continued). "HOX transcript antisense intergenic RNA (HOTAIR) was overexpressed in PDAC and HOTAIR knockdown in PDAC cells inhibited tumor growth in a mouse xenograft model suggesting a pro-oncogenic function for this lncRNA." (PMID 29657295, 2017). "HOTAIR expression level is also elevated in metastatic lung cancer, and higher expression promotes tumor cell motility and invasion." (PMID 27686732, 2016). "In conclusion, our studies demonstrated that miR-663b is epigenetically regulated by HOTAIR and exerts its tumor-suppressive function via targeting IGF2." (PMID 27895308, 2016). "Given the importance of HOTAIR in tumor progression we evaluated its expression in number of UBC cell lines ranging from Grade II to Grade IV." (PMID 26800519, 2016). "HOTAIR, a long non-coding RNA (lncRNA), plays a crucial role in tumor initiation and metastasis by interacting with the PRC2 complex and the modulation of its target genes." (PMID 27659532, 2016). "Patients with high expression of HOTAIR were more likely to have tumor recurrence and poor prognosis." (PMID 27143813, 2016). "lncRNAs such as HOTAIR are well known for the roles they play in tumor progression making them ideal as therapeutic targets as well as biomarkers." (PMID 26800519, 2016). "It was also reported that other EDs, such as the phytoestrogen genistein, inhibited HOTAIR by upregulation of miR-34 which targeted HOTAIR results in tumor-suppressive roles." (PMID 27023531, 2016). "HOTAIR overexpression (in SiHa cells) resulted in tumour growth rate increase via the Notch signalling pathway." (PMID 27323817, 2016). "In vivo xenograft experiments using the HOTAIR-overexpressing SiHa cell line revealed that HOTAIR was a strong inducer of tumour growth and modulated the expression of epithelial-mesenchymal transition and Notch-Wnt signalling pathway-related genes." (PMID 27323817, 2016). "Quantitative Real Time PCR (qRT-PCR) revealed that, in the unstimulated condition, tumor cells expressed variable levels of HOTAIR, MALAT1 and ANRIL." (PMID 27922078, 2016). "HOTAIR is involved in the control of cell apoptosis, growth, metastasis, angiogenesis, DNA repair, and tumor cell metabolism." (PMID 27835600, 2016). "HOTAIR is also frequently upregulated in oral squamous cell carcinoma and nasopharyngeal carcinoma, and overexpression is highly correlated with tumor metastasis, clinical stage, and poor prognosis." (PMID 27686732, 2016). "Additionally, increased levels of HOTAIR were associated with advanced tumor stages, adenocarcinoma, lymphatic vascular-space invasion, and lymphatic-node metastasis, and high serum levels of HOTAIR were significantly correlated with tumor recurrence and shorter overall survival." (PMID 27189224, 2016). "HOTAIR is is reported to reprogram chromatin organization and promote tumor progression and metastasis." (PMID 27167190, 2016). "In OSCC, HOTAIR was overexpressed in tumor tissues compared to normal tissues and its high expression was correlated to tumor size, clinical stage, lymphatic node metastasis, and histological differentiation." (PMID 27143813, 2016). "In nude mice ESCC models, HOTAIR promoted cell proliferation and tumor metastasis, while knockout reduced the metastasis of ESCC cells." (PMID 27686732, 2016). "In contrast, the time of xenograft tumor appearance was prolonged in the HOTAIR knockdown group compared to the control group (15.41 ± 4.12 days versus 9.74 ± 3.14 days, p < 0.01)." (PMID 26172293, 2015). "Morphologically, HE-stained slides indicated that HOTAIR knockdown induced shrinkage of tumor cell nuclei." (PMID 25823657, 2015). "HOTAIR overexpression resulted in early xenograft tumor formation compared to the control group (6.21 ± 1.61 days versus 9.23 ± 2.01 days, P < 0.05)." (PMID 26172293, 2015). "Other studies showed that high HOTAIR expression is accompanied with less differentiated histology, greater tumor depth, and liver metastasis." (PMID 26307974, 2015).
tumor (continued). "Other notatble lncRNAs such as HOTAIR, H19 and SRA become up-regulated with increasing EC tumour grade and other features associated with poor prognosis." (PMID 26556343, 2015). "On the other hand, when HOTAIR was knocked down, the average xenograft tumor weight decreased to approximately one third of the control weight (0.71 ± 0.13 grams versus 0.24 ± 0.06 grams, P < 0.01)." (PMID 26172293, 2015). "Given the well-recognized followup limitations of TCGA cohort, further studies are necessary to clarify the role of HOTAIR in metastases in cohorts well annotated for tumor histology, nodal status, and survival information." (PMID 25739705, 2015). "Two recent reports proposed that the role of HOTAIR in tumor progression and acquisition of invasiveness can involve an EMT process." (PMID 25861629, 2015). "When HOTAIR was overexpressed, the xenograft tumor weight increased approximately two folds when compared to the corresponding control group (1.35 ± 0.39 grams versus 0.65 ± 0.12 grams, P < 0.01)." (PMID 26172293, 2015). "The resulting depletion of HOTAIR expression in vivo significantly suppressed endometrial tumourigenesis and led to smaller tumour sizes." (PMID 26556343, 2015). "The in vivo study also demonstrated that knockdown of HOTAIR combined with miR-326 over-expression produced the smallest tumor and the longest survival in nude mice." (PMID 26183397, 2015). "HOTAIR overexpression was proven to promote metastasis and was correlated to poor prognosis of several tumor types, for example, breast, colorectal, and nasopharyngeal cancers and, particularly, it is overexpressed in HCC tissues and liver cancer cells." (PMID 25861629, 2015). "Of the many functions of HOTAIR, as tumor regulatory factors, the one for silencing HOTAIR transcription in CSCs has remained insufficiently understood." (PMID 25792974, 2015). "The tumor volume was smallest in the group of HOTAIR knockdown combined with miR-326 over-expression." (PMID 26183397, 2015). "We found that primary tumors in patients displaying tumor progression were characterized by increased HOTAIR levels." (PMID 26457124, 2015). "Patients with overexpressed HOTAIR had poorer prognoses and larger tumor sizes, more rapid proliferation of tumor cells." (PMID 25954300, 2015). "HOTAIR knockdown combined with miR-326 over-expression suppressed the tumor growth and had high survival rates in nude mice." (PMID 26183397, 2015). "The over expression of HOTAIR is predictive of poor patient prognosis and promotes tumor metastasis in epithelial ovarian cancer." (PMID 26631459, 2015). "For pure-SCLC cases, HOTAIR had a tendency to be expressed more in tumor tissues (n = 24) than normal tissues (n = 13) (P = 0.092)." (PMID 24591352, 2014). "Knockdown of HOTAIR in a murine xenograft model lead to a decrease in tumor volume and tumor weight." (PMID 25119862, 2014). "In tumorigenesis, HOTAIR acts as an oncogene; in tumor progression, HOTAIR promotes invasion and metastases." (PMID 25334066, 2014). "Increased expression of HOTAIR was also found in brain metastases compared to primary tumor samples." (PMID 25101115, 2014). "HOTAIR, which is one of the few well-studied lncRNAs, plays a significant role in tumor progression by regulation of oncogene or tumor suppressor gene expression through binding to PRC2." (PMID 25167886, 2014). "The lncRNA HOTAIR was up-regulated in gastric cancer tissue and correlated with larger tumor size, advanced pathological stage, distant metastasis, lymph node metastasis and inferior cell differentiation." (PMID 25119862, 2014). "Meanwhile, HOTAIR was involved in tumor progression and was regarded as a novel epigenetic molecular biomarker in patients with ESCC or CRC." (PMID 25058480, 2014). "The HOTAIR transcripts were expressed at higher levels in the tumor tissues compared with adjacent normal tissues (p < 0.0001), indicating that HOTAIR was frequently up-regulated in GBC." (PMID 24953832, 2014).
tumor (continued). "Specifically, HOTAIR expression was found to be significantly higher at later stages of tumor development and in tumors that had undergone extensive metastasis." (PMID 24103700, 2013). "Emerging evidence suggests that HOTAIR regulates the proliferation and metastasis of a variety of tumor cells." (PMID 23717443, 2013). "In conclusion, our results showed that genistein inhibits PCa cell growth through down-regulation of oncogenic HOTAIR that is targeted by tumor suppressor miR-34a." (PMID 23936419, 2013). "Our results indicated that genistein inhibited PCa cell growth through down-regulation of oncogenic HOTAIR that is also targeted by tumor suppressor miR-34a." (PMID 23936419, 2013). "This is the first report to investigate the correlation between HOTAIR expression and tumor chemoresistance." (PMID 24155936, 2013). "Our findings indicate that tumor-promoting Col-1 up-regulates the expression of HOTAIR in NSCLC cells." (PMID 23668363, 2013). "Next, qRT-PCR and Western blot assays were performed to detect the expression of HOTAIR and p21 protein in selected tumor tissues." (PMID 24155936, 2013). "In several candidate miRNAs targeting HOTAIR, we focused on miR-34a since our lab has been previously reported functions as a tumor suppressor and is down-regulated in PCa tissues." (PMID 23936419, 2013). "High levels of HOTAIR expression correlate with both metastasis and poor survival rate, connecting lncRNAs with tumor invasiveness and patient prognosis." (PMID 22613733, 2012). "Furthermore, HOTAIR exerts a simultaneous effect by activating oncogenes, such as cyclin D1, while repressing tumor suppressors like p21." (PMID 41020820, 2025). "Mechanistically, HOTAIR overexpression drives tumor progression by recruiting PCR2 and inducing H3K27me3 deposition on the promoters of suppressor genes; therefore, HOTAIR expression positively correlates with BC EMT transition, invasiveness and metastatic potential." (PMID 40141248, 2025). "Additionally, genistein directly targets HOTAIR, upregulating the tumor suppressor miR-34a, which in turn affects cell invasion, proliferation, and migration in PC3 and DU145 PCa cells." (PMID 39825964, 2025). "Additionally, non-coding RNAs, such as miR-21 and lncRNA HOTAIR, have been found to play roles in regulating SqD and tumor progression." (PMID 39857670, 2025). "Moreover, in vivo findings demonstrated that PPI triggers inhibition of tumour growth, HOTAIR and the protein expressions of DNMT1 and EZH2." (PMID 40387409, 2025). "By interacting with key factors in the Notch signaling pathway (such as NICD)lncRNAs like HOTAIR (HOX transcript antisense RNA) and MALAT1 (metastasis-associated long non-coding RNA transcript 1) promote tumor progression through three-dimensional genomic reorganization." (PMID 40621472, 2025). "Additionally, HOTAIR has been found to upregulate the expression of key oncogenes by inhibiting the functional binding of miRNAs, providing a survival advantage to tumor cells." (PMID 40235720, 2025). "For example, simultaneously inhibiting an oncogenic lncRNA that promotes proliferation (e.g., HOTAIR) and delivering a tumor-suppressive miRNA mimic that enhances apoptosis or immune recognition (e.g., miR-34a) might yield greater efficacy." (PMID 41221298, 2025). "Finally, the identification of a molecule that can regulate two of the most important and complementary metabolic pathways in tumor cells suggests that HOTAIR plays a crucial role in metabolic reprogramming." (PMID 40072116, 2025). "In addition to the pro-tumorigenic effects, several recent studies indicate that HOTAIR signaling plays prominent roles in conferring chemoresistance to tumor cells." (PMID 38366205, 2024). "Indeed, alterations in the HOTAIR-miR-141-SKA2 signaling axis by either knockdown of HOTAIR lncRNA or overexpression of miR-141 results in inhibition of growth of ectopic tumor xenografts in mice." (PMID 38366205, 2024).
tumor (continued). "In addition, in CRC xenograft tumours, HOTAIR silencing increased the radiosensitivity through the modulation of autophagy mediated by miR-93/ATG12 axis." (PMID 38887279, 2024). "Similarly, overexpression of HOTAIR in oral squamous cell carcinomas is implicated in increased EMT and invasiveness of tumor cells, while its ablation rescues cellular stemness and tumorigenicity of oral carcinoma cells." (PMID 38366205, 2024). "HOTAIR is a critical regulator in EC, contributing to tumor growth and poor prognosis." (PMID 38981872, 2024). "This suggests that inhibiting HOTAIR and MALAT1 may affect the anti-inflammatory activity of tumour-associated macrophages in these tumours (Amer, Eissa and El Tayebi, 2022)." (PMID 38887279, 2024). "Additionally, HOTAIR has been found to interact with miR‐193a, influencing tumour cell growth and invasion." (PMID 39347925, 2024). "Moreover, a positive correlation was identified between HOTAIR levels in tumor tissue and in the peripheral blood of HCC patients." (PMID 39596302, 2024). "In the present study, we found that HOTAIR may be a useful tumor marker for diagnosing HBV-related HCC." (PMID 39128100, 2024). "Moreover, they proposed HOTAIR as a potential marker for tumor grade as its expression was found to be strongly and positively correlated with the tumor grade and severity." (PMID 38366205, 2024). "By staging patients according to their HOTAIR expression levels in HCC tissue, the authors demonstrated that patients with high HOTAIR expression exhibited a markedly poorer prognosis, reduced OS, and a significantly larger tumor size than those with low HOTAIR expression." (PMID 39596302, 2024). "Furthermore, it is asserted that in HPV16-related OC, the HPV E7 protein positively regulates the expression of the lncRNA HOTAIR, while reducing HOTAIR expression upregulates HOXD10 to affect the proliferation of tumor cells." (PMID 38071681, 2024). "Furthermore, the expression level of HOTAIR also can reflect the immune infiltration level of tumor tissues." (PMID 38696320, 2024). "Interestingly, the authors identified a correlation between the HOTAIR expression and tumour stem cell formation." (PMID 38887279, 2024). "Furthermore, HOTAIR is involved in the control of the release of exosomes by the cell, potentially affecting cell-cell communication in the tumor microenvironment." (PMID 37308974, 2023). "Additionally, high HOTAIR levels correlated with higher tumor grade and presence of lymph node metastases." (PMID 37370745, 2023). "HOTAIR seems to be an oncogene that plays a critical role in tumor progression." (PMID 37424727, 2023). "HOTAIR and its associated protein-coding gene HOXC were also found to be overexpressed in atypical teratoid/rhabdoid tumor (ATRT) tissues, a rare neoplasm characterized by heterogeneous cells resembling embryonic and muscular cells, although the underlying mechanism needs further investigation." (PMID 38004481, 2023). "Moreover, suppressing lncRNA HOTAIR curbs MB cell proliferation, tumor growth, migration, and invasion while promoting apoptosis via the miR-1/miR-206-YY1 axis and EMT." (PMID 38004481, 2023). "Besides that, PTEN methylation is one of the epigenetic modifications that is involved in tumor progression; HOTAIR enhances tumor growth in LSCC cells by inducing PTEN methylation." (PMID 37644548, 2023). "In vivo analysis has demonstrated that the knockdown of HOTAIR can inhibit tumor growth." (PMID 36997931, 2023). "HOTAIR has also been reported to exploit the ceRNA mechanism to regulate tumor progression." (PMID 37240232, 2023). "Although direct evidence linking HOTAIR to autophagy in the tumour promoting and drug resistance effects of CML is currently lacking, it is worth exploring the relationship between HOTAIR and autophagy considering the close association between the PI3K/AKT/mTOR pathway and apoptosis with autophagy." (PMID 37837401, 2023).
tumor (continued). "In addition, CAFs-derived CCL5 can promote tumor resistance to CDDP by upregulating the expression of lncRNA HOTAIR." (PMID 37666813, 2023). "Earlier research found HOTAIR participates in multiple tumor forming and metastasis pathways." (PMID 36816362, 2023). "Since, in contrast to HOTAIR, miR-141 is a tumor suppressor, its interaction with HOTAIR may have an impact on the process of malignant transformation, which may also include breast carcinogenesis." (PMID 37175800, 2023). "Likewise, elevated expression levels of oncogenic LncRNAs such as ANRIL and HOTAIR were observed in the serum samples and clinical tumor tissues of breast cancer patients compared to their paired healthy controls." (PMID 36770654, 2023). "This study observed that silencing HOTAIR preventes tumor growth in a xenograft model, while the silencing of miR-129-5p reversed HOTAIR gene silencing effects and FZD7 reinstated the inhibitory effect of miR-129-5p, suggesting that HOTAIR regulates the miR-129-5p/FZD7 axis." (PMID 36997931, 2023). "HOTAIR also contributes to tumor growth by negatively regulating miR-20a-5p." (PMID 36997931, 2023). "Thus, HOTAIR can affect the liver’s ability to metabolize tumor drugs by affecting the binding of miR-206/miR-613 to OATP1B1." (PMID 35093153, 2022). "HOTAIR can also affect the invasion and metastasis of tumor cells by adsorbing miR-217-5p." (PMID 35093153, 2022). "Furthermore, the knockdown of HOTAIR has been shown to improve the sensitivity of tumour cells to cisplatin and doxorubicin." (PMID 35052495, 2022). "Furthermore, HOTAIR carried by serum-EVs promoted tumor growth and TMZ resistance in vivo by suppressing miR-526b-3p-mediated EVA1 inhibition." (PMID 35418162, 2022). "Studies have shown that HOTAIR knockdown in different tumor cells could affect EZH2-dependent cell cycle expression and induce cell cycle arrest." (PMID 35813070, 2022). "In the current study, we investigated whether HOTAIR-mediated epigenetic alterations participate in enacting long-term epigenetic memory using transgenic iHOT+ tumor cells." (PMID 36579891, 2022). "In addition, HOTAIR (HOX transcript antisense RNA) is the first lncRNA found to promote tumor progression." (PMID 36387279, 2022). "In addition, lincRNA-p21 has been described as a tumor suppressor, while HOTAIR, MALAT-1, H19, PVT1, ANRIL, and GIHCG, have been characterized as oncogenic lncRNAs." (PMID 36360316, 2022). "In the prognostic PRlncRNA risk model, 8 lncRNAs (HOTAIR, LINC00402, SFTA1P, LINC00461, DSCR8, CYP1B1-AS1, LINC00330, ALMS1-IT1) were upregulated, while the other 3 lncRNAs (ZRANB2-AS1, MYB-AS1, TP53TG1) were downregulated in tumor tissues." (PMID 35413978, 2022). "An elevated HOTAIR expression is associated with resistance to chemotherapeutics, suggesting that inhibitors of HOTAIR could potentially resensitize a patient’s tumor to a specific chemotherapy." (PMID 35406713, 2022). "HOTAIR can promote the proliferation of various tumor cells by regulating miRNA." (PMID 35093153, 2022). "High expression of HOTAIR promotes tumor growth and carries a dismal prognosis for the patient." (PMID 35347094, 2022). "The results showed that MEG3 and HOTAIR expression levels could discriminate tumor from non-tumor tissues with specificities 86% and 74%, and sensitivities 79% and 84% respectively." (PMID 35186192, 2022). "The knockdown of HOTAIR in these cells led to the inhibition of tumor cell growth and invasiveness." (PMID 35052495, 2022). "The role of HOTAIR in tumor-initiating formation was next explored." (PMID 36273585, 2022). "Previous studies have revealed that HOTAIR is upregulated in GC tumor tissues." (PMID 34923813, 2022). "Altogether, HOTAIR silencing slowed down the tumor growth by inactivating the PI3K/AKT pathway." (PMID 35248107, 2022). "HOTAIR interacts mainly with miRNAs influencing tumor initiation and development." (PMID 39086963, 2022).